SPOP (speckle type BTB/POZ protein)
Diseases named in the same sentence as SPOP in open-access papers (continued):
Sharing a sentence is not in itself a finding about the gene and the disease.
endometrial cancer (38 papers, 2015 to 2025). Primary or metastatic malignant neoplasm involving the endometrium (mucous membrane that lines the endometrial cavity). "Mutations in SPOP found in endometrial cancer compromise its ability to mediate ERα degradation and ubiquitination." (PMID 40521202, 2025). "While endometrial cancer-specific SPOP mutations enhance BET protein degradation and sensitize cells to BET inhibitors, PCa-specific mutations hinder this degradation, leading to increased resistance." (PMID 40521202, 2025). "Among the candidates, SPOP, which has been implicated in immune evasion in liver and endometrial cancers, was prioritized." (PMID 40483310, 2025). "The gene encoding the E3 ubiquitin ligase substrate-binding adaptor SPOP is frequently mutated in endometrial cancer (EC), and it is also one of the factors driving the progression of EC." (PMID 40740763, 2025). "A previous study revealed that SPOP mutations promote tumor immune escape through the IRF1–PD-L1 axis in endometrial cancer." (PMID 40740763, 2025). "In contrast, endometrial cancer-associated SPOP mutants fail to degrade IRF1 and instead promote its stabilization, leading to enhanced PD-L1 expression." (PMID 40521202, 2025). "In cancers such as prostate, renal carcinoma, and endometrial cancer, SPOP mutations are often clustered in the MATH domain, leading to loss-of-function or gain-of-function alterations 31,35,36." (PMID 40521202, 2025). "Functionally, endometrial cancer-associated SPOP mutations accelerate xenograft tumor growth, partially by augmenting IRF1 and PD-L1 levels." (PMID 40521202, 2025). "Systematical sequencing studies have revealed high-frequency mutations of SPOP in several types of human tumors, particularly in prostate and endometrial cancers." (PMID 38409107, 2024). "Recurrent missense mutations in SPOP have been found in 5–10% of prostate and endometrial cancers in comprehensive genome sequencing studies." (PMID 38308184, 2024). "A recent study analyzes the cryo-electron microscopic structure of SPOP and finds that E47K endometrial cancer mutation increases SPOP stability, while W22R endometrial cancer mutation alters its quaternary structure." (PMID 38409107, 2024). "For instance, the speckle-type POZ protein, SPOP, is a zing finger protein with an oncogenic role that is frequently mutated in prostate and endometrial cancers." (PMID 39201255, 2024). "The initial identification of SPOP stemmed from its correlation with prevalent mutations observed in prostate and endometrial cancers, especially within the MATH domain, leading to the destruction or decrease of substrate affinity." (PMID 37796126, 2023). "In prostate and endometrial cancers, SPOP mutations appear to confer either sensitivity or resistance against first generation BET inhibitors, depending on the tumor type." (PMID 36313707, 2022). "Of note, mutations in SPOP that affect substrate binding are associated with prostate and endometrial cancers, among others, and so the study of SPOP and its interacting partners has broad implications across many fields." (PMID 33894201, 2021). "The pathophysiological functions of the endometrial cancer-associated SPOP mutants are still controversial." (PMID 33023230, 2020). "Prostate and endometrial cancer-associated SPOP mutations lose and increase substrate-binding ability, respectively." (PMID 33023230, 2020). "Pathologically, missense mutations in the substrate-binding domain of SPOP have been found in prostate and endometrial cancers." (PMID 33023230, 2020). "In contrast, endometrial cancer-associated SPOP mutations increase the ability of substrate binding, leading to enhanced polyubiquitination of the substrate proteins, followed by their degradation." (PMID 33023230, 2020). "The identified SPOP variant is noted as a likely oncogenic mutation in 1.2% of the TCGA dataset for endometrial cancer, all corresponding to patients who are living and have all been disease-free for greater than 24 months." (PMID 29254223, 2017).
endometrial cancer (continued). "In some other types of cancer with a high frequency of SPOP mutation, such as prostate and endometrial cancers with 8–14% rate of SPOP mutation, little is known about how SPOP mutations influence the stability of its substrates." (PMID 28032859, 2016). "Our results provide a functional insight into the molecular mechanism of endometrial cancer pathway involved with SPOP mutations." (PMID 25766326, 2015). "Mutations of the residues at MATH domain substantially decreased the capacity of SPOP to interact with ERα in vivo, suggesting the endometrial cancer-associated SPOP mutants are defective in binding to ERα." (PMID 25766326, 2015). "Taken together, our findings suggest that endometrial cancer-associated mutants of SPOP are defective in promoting ERα degradation and ubiquitination." (PMID 25766326, 2015). "SPOP was mutated in 5.7–10% of patients with endometrial cancer across multiple independent cohorts." (PMID 25766326, 2015). "Recurrent SPOP mutations in endometrial cancer have been confirmed by four independent genome-wide studies." (PMID 25766326, 2015). "Strikingly, endometrial cancer-associated mutants of SPOP are defective in regulating ERα degradation and ubiquitination." (PMID 25766326, 2015). "Recently, several exome-sequencing studies of endometrial cancer revealed high frequency somatic mutations in SPOP (5.7–10%)." (PMID 25766326, 2015). "Endometrial cancer-associated mutants of SPOP are defective in promoting ERα degradation and ubiquitination." (PMID 25766326, 2015). "We then examined the capacities of endometrial cancer-associated SPOP mutants in promoting ERα degradation." (PMID 25766326, 2015). "However, endometrial cancer -associated SPOP mutants exhibit impaired regulation of ZBTB3 stability." (PMID 40521202, 2025). "IRF1 is essential for tumor immune evasion caused by SPOP mutations in endometrial cancer." (PMID 38789431, 2024). "Another study has found high frequencies of somatic mutations in SPOP in endometrial cancers (ECs)." (PMID 38409107, 2024). "Moreover, PTEN is found to be strongly mutually exclusive with SPOP, whose mutations are also associated with endometrial cancer." (PMID 34899838, 2021). "Speckle type BTB/POZ protein (SPOP) is one of the highest loci to exhibit loss of heterozygosity in breast cancers and has high mutation rates in prostate and endometrial cancers." (PMID 29594129, 2018). "Our study revealed novel molecular mechanisms underlying the regulation of ERα protein homeostasis in physiological and pathological conditions, and provided insights in understanding the relationship between SPOP mutations and the development of endometrial cancer." (PMID 25766326, 2015). "Thus, our findings suggest that wild-type SPOP can suppress endometrial cell proliferation, and this suppression is abrogated by endometrial cancer-associated SPOP mutations." (PMID 25766326, 2015). "Although frequent mutations of SPOP in endometrial cancer have been identified, the functional impact of these mutations remains unknown." (PMID 25766326, 2015). "Moreover, SPOP mutations were detected in three major histological subtypes of endometrial cancer (endometrioid, clear cell and serous)." (PMID 25766326, 2015). "Notably, all the SPOP mutations found in endometrial cancer far-exclusively occur in the MATH domain which is responsible for ERα binding." (PMID 25766326, 2015). "For future studies, it will be useful to generate mice models of conditional endometrial-specific SPOP knockout or knockin to further characterize the phenotype of SPOP mutations in vivo, and determine whether ERα pathway is dysregulated in SPOP mutated endometrial cancer." (PMID 25766326, 2015). "Therefore, we propose that endometrial cancer-associated SPOP mutations may cause dysfunction in regulating ERα protein level." (PMID 25766326, 2015).
endometrial cancer (continued). "Specifically, endometrial cancer-specific SPOP mutants, which markedly reduce BET protein levels, increase endometrial cancer cells' sensitivity to BET inhibitors by promoting apoptosis and suppressing proliferation." (PMID 40521202, 2025). "SPOP functions predominantly as a tumor suppressor in prostate, lung, gastric, liver, colon, and endometrial cancers 14,24, but acts as an oncogene in clear cell renal cell carcinoma (ccRCC) 14,31." (PMID 40521202, 2025). "In summary, the differential impact of SPOP mutations on BET protein degradation highlights a context-dependent mechanism that distinctly influences therapeutic responses in prostate and endometrial cancers." (PMID 40521202, 2025). "Recently, the SPOP has also been identified as a key negative regulator of the IRF1-PD-L1 axis in endometrial cancer." (PMID 40521202, 2025). "In endometrial cancer, SPOP mutations alter estrogen receptor-α stability and enhance BET protein degradation, SPOP also regulates multiple substrates, including SRC-3, progesterone receptor, and c-Myc, to exert tumor-suppressive effects 12, 38-40." (PMID 40657370, 2025). "Speckle-type POZ protein (SPOP) is an adaptor of the cullin-RING-based E3 ubiquitin ligase complex that is frequently mutated in prostate and endometrial cancers." (PMID 39062505, 2024). "Previous studies have demonstrated that SPOP acts as a tumor suppressor in prostate and endometrial cancers, while it exhibits a tumor-promoting role in kidney cancer." (PMID 37796126, 2023). "Gain of SPOP function causes enhanced polyubiquitination and subsequent degradation of BET proteins in endometrial cancer cells, arguing for a tumor suppressive role for SPOP." (PMID 33327527, 2020). "A recent study indicated that SPOP mutants has cancer specific preference in endometrial cancer to degrade BET family proteins." (PMID 30237511, 2019). "Taken together, these findings provide new insights in our understanding of the physiological and pathophysiological significance of SPOP in regard to the development of endometrial cancer." (PMID 25766326, 2015). "Taken together, these data suggest that SPOP has an important role in estrogen-induced ERα degradation and transactivation in endometrial cancer cells." (PMID 25766326, 2015). "However, how SPOP mutations contribute to endometrial cancer remains unknown." (PMID 25766326, 2015). "ERα plays a central role in promoting endometrial cancer and serves as a substrate for SPOP." (PMID 40521202, 2025). "Moreover, SPOP also plays a role in estrogen-driven ERα degradation and transactivation, highlighting its multifaceted involvement in endometrial cancer progression." (PMID 40521202, 2025). "Notably, SPOP mutations associated with PCa inhibit BET protein degradation, while mutations associated with endometrial cancer paradoxically enhance BET protein degradation through a gain-of-function mechanism." (PMID 40521202, 2025). "Notably, ZBTB3 regulates the transcription of sonic hedgehog (SHH), with SPOP inactivation leading to ZBTB3-dependent SHH upregulation in endometrial cancer cells." (PMID 40521202, 2025). "Indeed, SPOP targets different substrates and acts as a suppressor in prostate and endometrial cancers and as a promoter in kidney cancer." (PMID 32235916, 2021). "In this study, we demonstrated that SPOP forms a functional CUL3-SPOP-RBX1 E3 ubiquitin ligase complex which targets ERα for ubiquitination and proteasomal degradation in endometrial cancer cells." (PMID 25766326, 2015). "Moreover, a specific endogenous interaction between SPOP and BRAF was observed in Ishikawa endometrial cancer cells." (PMID 36585710, 2022).
prostate tumors (27 papers, 2014 to 2025). "A preclinical study of prostate tumors showed that 10%–15% had SPOP mutations, and palbociclib promoted SPOP degradation by preventing phosphorylation of SPOP mediated by D-CDK4." (PMID 37305685, 2023). "For example, prostate tumor samples with SPOP mutations have been associated with the overexpression of SPINK1 through activating the mitogen-activated protein kinase (MAPK) pathway." (PMID 36937425, 2023). "SPOP was also positively associated with age in prostate tumours (PCAWG adjusted LGR p = 0.099, AACR GENIE adjusted LGR p = 0.03)." (PMID 35017538, 2022). "We screened for somatic variants in Exons Six and Seven of the SPOP gene in the prostate tumor tissues, as all the previously reported SPOP mutations were within these two exons." (PMID 34322378, 2021). "Not surprisingly, several clinical studies have shown that patients with prostate tumors bearing SPOP mutations are highly sensitive and show better response to androgen signaling inhibitors therapy, nevertheless it does not translate to survival benefit." (PMID 33158056, 2020). "Up to 13% of prostate tumors were reported to harbor SPOP mutations and this tumor subtype shows a distinct pattern of genomic alterations." (PMID 26863016, 2016). "Recent large-scale somatic mutation studies revealed that SPOP is one of the most frequently mutated genes in human prostate tumors." (PMID 24508459, 2014). "Systematic whole-genome or exome sequencing of prostate tumors has led to the identification of frequent somatic mutations in SPOP." (PMID 24508459, 2014). "GLI3 levels are significantly higher in prostate tumors with SPOP mutations." (PMID 40432836, 2025). "For example, CHD1 deletions and SPOP mutations frequently co-occur in prostate tumors." (PMID 36937425, 2023). "Furthermore, when comparing prostate tumor specimens with SPOP mutations to those with wild-type SPOP, SENP7 is expressed at higher levels, and SENP7 depletion causes PCa cells to become senescent." (PMID 35887358, 2022). "Importantly, a vast majority of prostate tumors that lack SPOP mutations still show reduced SPOP levels, implying that SPOP downregulation is essential for PCa progression." (PMID 33158056, 2020). "In addition to mutations, SPOP protein expression is often downregulated in prostate tumors." (PMID 24508459, 2014). "To further assess the impact of SPOP mutations on LMNB2 protein levels in patient specimens, we analyzed 100 primary prostate tumors from our cohort." (PMID 40662365, 2025). "Given the context-dependent role of CHD1 in prostate tumors, genes showing co-occurrence (SPOP or MAP3K7) or mutual exclusivity (ERG and PTEN) should also be considered as influence factors in these clinical studies." (PMID 36776288, 2023). "Phenocopying CHD1 loss, SPOP mutations also cause genomic instability and impaired HR DSB repair, as well as promote the sensitivity of prostate tumors to DNA-damaging therapeutic agents, such as PARP inhibitors." (PMID 36776288, 2023). "We conclude that G3BP1high and SPOP mutations are two oncogenic means that function either independently or jointly to disable the tumor-suppressive role of SPOP and promotes prostate tumor progression." (PMID 34795264, 2021). "Here, the authors show that mutations in SPOP render prostate tumor cells sensitive to antiandrogen therapy and that the presence of ERG promotes sensitivity to high dose of androgen and SPOP inhibition." (PMID 33531470, 2021). "Since the SPOP mutations behave as loss of function mutants in cell line experiments, it will be important to determine in future experiments the relative abundance of mutant and wild type SPOP protein present in prostate tumor tissues." (PMID 28810879, 2017). "Protein expression levels of all three analyzed autoantigens, SPAST, STX18 and SPOP were significantly deregulated either in primary prostate tumors and/or in late, castration-resistant tumor stages." (PMID 26863016, 2016).
prostate tumors (continued). "Another study in AA men revealed that, compared to cases with either alteration alone, prostate tumors with both CHD1 deletion and SPOP mutations showed significantly higher levels of HR deficiency-associated signatures and large-scale structural rearrangements." (PMID 36776288, 2023). "Loss of the CHD1 and MAP3K7 genes can also promote the development of prostate tumors in the absence of SPOP mutations." (PMID 26506153, 2015). "Western blot analysis confirmed three isogenic LNCaP lines corresponding to SPOP mutant, TRIM28-high, and TRIM28-low prostate tumors." (PMID 30479348, 2018). "ZBTB38 mRNA expression, in combination with other genetic alterations (i.e., SPOP/SPOPL), might thus be useful to identify localised prostate tumours that will exhibit more aggressive behaviour and target metastasis with doxorubicin-based therapies." (PMID 32365491, 2020). "In fact, RGMB-AS1 was most frequently altered in this cancer type, and SPOP was altered in 12% of samples in the PRAD TCGA cohort, though according to some publications, SPOP could be altered in up to 15% of prostate tumors." (PMID 33333852, 2020). "Furthermore, it is of note that the five prostate tumors putatively identified with the tandem duplication genotype were ETS rearrangement negative, CHD1 wild-type, and where genotyping was carried out, SPOP wild-type (tumor T4 was also CHD1 and SPOP wild-type)." (PMID 25155515, 2014).